RNF183 (ring finger protein 183)
Diseases named in the same sentence as RNF183 in open-access papers (continued):
Sharing a sentence is not in itself a finding about the gene and the disease.
tumor (8 papers, 2015 to 2025). "RNF183 high expression is significantly associated with tumor size (P=0.012), tumor invasive depth (P=0.004), TNM stage (P=0.01), and distant metastasis (P=0.009)." (PMID 28796265, 2017). "RNF183 high expression was significantly associated with tumor size (P=0.012), tumor invasive depth (P=0.004), TNM stage (P=0.01), and distant metastasis (P=0.09)." (PMID 28796265, 2017). "Subsequently, we monitored apoptotic markers and found that with FBXO5 silencing, increased expression of RNF183 led to augmented Caspase3/7 activity, leading tumor cells towards apoptosis." (PMID 38212299, 2024). "RNF183 is primarily localized in the endoplasmic reticulum (ER) and plays a crucial regulatory role in cell survival and apoptosis, ultimately impacting tumor development." (PMID 38212299, 2024). "When we quantified two proteins in all samples, 62.5% (26/40) of Bcl-xL was higher, whereas 77.5% (31/40) of RNF183 was lower in tumor tissues compared to adjacent normal tissues." (PMID 35121737, 2022). "Based on the marker levels of different immune cell types in UCEC, RNF183 mRNA level is correlated with the number of tumor infiltrating immune cells, which indicates that RNF183 plays a vital role in regulating tumor immunity." (PMID 33324448, 2020). "On the side of immunization, high level of RNF183 in UCEC is negatively related to tumor purity, infiltrating levels of CD4 + T cells, neutrophils, and dendritic cells." (PMID 33324448, 2020). "The RNF183 expression was greater at higher expression and the tumor stage was greater at the lower level." (PMID 33324448, 2020). "Given that epithelial–mesenchymal transition (EMT) is a critical event involved in the initiation of tumor invasion, the impact of RNF183 on the expression of several EMT markers was analyzed in HCT116 cells." (PMID 28796265, 2017). "Enforced expression of RNF183 promotes proliferation, invasion, and metastasis of tumor cells, whereas opposite phenomenon were observed in RNF183 knockdown experiments, indicating that RNF183 functions as an oncogene in the pathological process of CRC." (PMID 28796265, 2017). "Here, we reanalyzed the expression of 202 RNF family members in CRC using published microarray data from GEO database and found that RNF183 is markedly upregulated in tumor tissues." (PMID 28796265, 2017). "In a separate NSCLC data set, the majority of tumours with highFATE1 expression also exhibited elevated RNF183 expression, and again, highexpression of both genes predicted shortened overall survival time(HR=2.80; P<0.0001; Cox Regression)." (PMID 26567849, 2015). "Furthermore, silencing RNF183 enhanced the proliferative capacity of tumor cells and restored the proliferation ability of cells following FBXO5 silencing." (PMID 38212299, 2024). "We speculate that RNF183, which is highly expressed in the tumor microenvironment, leads to a better prognosis of UCEC by regulating the expression of inhibitory immune checkpoint proteins PD-1, LAG3 and GZMB on exhausted T cells." (PMID 33324448, 2020). "The results show that RNF183 expression has negatively correlations with tumor purity (r = −0.063, p = 2.85E–01), infiltrating levels of CD4 + T cells (r = −0.064, p = 2.74E–01), neutrophils (r = −0.126, p = 3.17E–02), and dendritic cells (r = −0.042, p = 4.78E–01)." (PMID 33324448, 2020). "Above indicate the role of RNF183 in regulating tumor invasion of T helper cells." (PMID 33324448, 2020). "Our analyses revealed significant increased expression of RNF183 in tumor tissues." (PMID 28796265, 2017). "The results showed that RNF183 enforced expression significantly promote tumor growth." (PMID 28796265, 2017). "Finally, xenograft tumor model showed the synergism of RNF183 knockdown and trametinib in repressing the growth of CRC cells in vivo." (PMID 28756770, 2017).
tumor (continued). "In accordance with previous reports that NF-κB signal pathway and its downstream chemokine IL-8 contributes to inflammation and to every step of CRC progression proliferation, migration and invasion, we found that NF-κB inhibition and IL-8 depletion eliminates the tumor-promoting activity of RNF183." (PMID 28796265, 2017). "In the nucleus, NF-κB promotes cell survival by upregulating ring finger protein 183 (RNF183), which mediates the degradation of the anti-apoptotic protein Bcl-xL, thereby facilitating tumor growth." (PMID 40699764, 2025). "By mediating ubiquitination-mediated degradation of RNF183, FBXO5 prevents ER stress-induced apoptosis and facilitates tumor growth." (PMID 38212299, 2024). "The expression levels of RNF183 were downregulated in RCC tissues, while Bcl-xL expression was upregulated in RCC tumor tissues." (PMID 35121737, 2022). "Our results indicate that RNF183 is a potential independent prognostic biomarker of UCEC, which can also be used to assess the level of immune cell infiltration in tumor tissues." (PMID 33324448, 2020). "Here, we report that RNF183 is an independent prognostic factor in CRC patients, and high RNF183 level is closely related to tumor size, invasive depth, TNM stage and distant metastasis." (PMID 28796265, 2017). "Functional studies suggest that RNF183 facilitates growth, migration, and invasion of CRC cells in vitro and promotes tumor proliferation and metastasis in vivo." (PMID 28796265, 2017). "The frequency of co-expression of RNF183 and FATE1 alongwith their correlation with poor outcome reinforces the notion that theseproteins are functioning in human tumours to promote survival." (PMID 26567849, 2015). "Furthermore, when RNF183 was silenced in conjunction with FBXO5, tumor growth was restored, as evidenced by consistent conclusions drawn from statistical analyses of tumor volume and weight." (PMID 38212299, 2024). "The expression of RNF183 is significantly higher in tumor tissues than in adjacent non-tumor tissues." (PMID 28796265, 2017).
infection (1 paper, 2017). The state of being infected such as from the introduction of a foreign agent such as serum, vaccine, antigenic substance or organism. "Stable RNF183-knockdown cell lines were generated by infection of lentiviruses that express RNF183 shRNA, and small interference RNA (siRNA) was used to knock down RNF183 transiently." (PMID 28756770, 2017).
RNF183 also shares sentences with these, for which no sentence is quoted: Crohn disease (1 paper); diabetic nephropathy (1); endometrial tumors (1); Hyperglycemia (1); inflammation (1); kidney disease (1); lymph node metastasis (1).